CD4 (CD4 molecule)
Diseases named in the same sentence as CD4 in open-access papers (continued):
Sharing a sentence is not in itself a finding about the gene and the disease.
tumor (continued). "Modifying the tumor microenvironment to hinder the infiltration of myeloid-derived suppressor cells (MDSCs) promoted the differentiation of M1 macrophages which, in turn, facilitated the differentiation of Th1 cells and augmented the population of activated CD4+ and CD8+ T cells." (PMID 38715617, 2024). "Additionally, tumor imaging revealed that these patients may also lack the presence of other key immune cell types such as CD4 T cells and B cells to help confer an anti-tumor response." (PMID 39190534, 2024). "Therefore, we further used flow cytometry to analyze immune cell infiltration in endpoint tumors, indicating that the percentage of CD206+ ST2L+ M2 macrophages, M2/M1 ratio and CD4+ Foxp3+ Tregs were higher in tumor allografts from the cisplatin monotherapy group." (PMID 38778059, 2024). "However, depletion of either CD4+ or CD8+T cells abolished the function of Esm1 on tumor growth." (PMID 38956432, 2024). "For instance, the existence of CD4+CD25+Foxp3+ regulatory T cells has been associated with unfavorable survival rates, implying that these cells might contribute to malignancy progression by dampening anti-tumor immunological defenses." (PMID 39267764, 2024). "Additionally, intratumoral injection of λ-carrageenan stopped the growth of tumours in mice with mammary and melanoma tumours, and it improved the immune response to tumours by increasing the release of dendritic cells, activated CD4 + CD8 + T lymphocytes, and tumour-infiltrating M1 macrophages." (PMID 39312045, 2024). "Notably, the combination of ONCOS-204 and EGFRxCD3 BsAb exhibits superior ability in augmenting T cell activation and cytotoxicity compared to ONCOS-102, with ONCOS-204 particularly significantly influencing CD4+ T cell subpopulations infected with tumor cells." (PMID 39055561, 2024). "In conclusion, modalities that increase CD8+ and CD4+ T lymphocyte responses, including the protein products produced by innate immune cells, such as eosinophils and ILC2s, may increase anti-tumor responses and reduce tumor growth." (PMID 38524132, 2024). "Furthermore, CD4+ T-cells exhibit direct tumor suppression through various IFN-γ functionalities." (PMID 38671743, 2024). "Therefore, the aim of this study is to determine whether HVEM has an inhibitory effect on anti-tumor CD4+ T cell responses in vitro and whether HVEM gene expression is dysregulated in patients with ALL." (PMID 38785930, 2024). "Therefore, we turned toward assessing whether tumor-intrinsic Aurora-A can promote CD8+ T cell activity by regulating CD4+ T cells." (PMID 38291041, 2024). "Additionally, anti–PD-1 and anti–CTLA-4 ICIs are known to have distinct mechanisms of action, with anti–CTLA-4 agents more capable of activating and expanding T cells, particularly CD4+ T cells, in the tumor draining lymph nodes, leading to increased trafficking of activated T cells into the TME." (PMID 39561007, 2024). "Additionally, we observed that elevated expression levels of the CD4+ Tcm cluster signature and reduced expression of the exhausted CD8+ cluster signature reflected differences in the tumor immune infiltrate composition and were associated with positive treatment outcomes." (PMID 39123475, 2024). "Thus, prior ipilimumab induction may trigger intra-tumoral recruitment of CD4+/CD8+ T cells from peripheral blood or tumor parenchyma switching tumor microenvironment from immune-excluded/desert to immune-inflamed status, so called from “cold” to “hot” status." (PMID 38448521, 2024). "Interestingly, we observed a 2.3-fold increase in the percentages of proliferative Ki-67+CD8+ T cells, as well as a 1.7-fold increase in TCF-1+CD8+ and 2.5-fold increase in TCF-1+CD4+ T cells, which have been attributed a function in the persistent control of tumor growth." (PMID 39236156, 2024). "Furthermore, its anti-tumor immune responses encourage the depletion of FOXP3+CD4+ Tregs." (PMID 36721212, 2023).
tumor (continued). "Of note, neoantigen‐specific CD4+ T cells may also play a role in anti‐tumour immunity." (PMID 37921274, 2023). "Moreover, elevated KCNA3 levels were inversely correlated with the presence of dendritic cells (both active and resting), natural killers (NKs), CD4+ T cells, and mast cells, which were all able to favor recognition, antigen presentation, and killing of tumor cells." (PMID 36978819, 2023). "In addition to the Tregs, CD154-expressing CD4+ T cells were increased during tumor progression." (PMID 36828832, 2023). "Second, ANGPTL8 could also interact with PIRB in macrophages (Kupffer cells) to upregulate Fgr expression and drive macrophage polarization into the M2 phenotype to suppress anti-tumor immune responses by increasing the number of CD4+FOXP3+ and CD8+PD-1+ T cells in the tumor microenvironment." (PMID 37188659, 2023). "Furthermore, it has been shown that both the infiltration of CD4+ T cells and CD8+ T cells is associated with improved overall survival (OS) and disease-free survival (DFS) in PDAC; however, the TME of PDAC tumours have poor infiltration of CD4+ and CD8+ lymphocytes." (PMID 37190281, 2023). "Prior research has documented that CD4 memory T cells may inhibit the progression of tumors by upregulating the proliferative ability of CD8T cells, which differentiate into effector cells following their migration into tumor-associated tissues." (PMID 37876593, 2023). "Confocal microscopy revealed local accumulations of eGFP+ TRP-1 CD4+ T cells in association with MHC-II-expressing CD11c-Venus+ immune cells within tumour invasive margins in HCmel12 CRISPR-ctrl but not in HCmel12 Trp1-KO tumours." (PMID 37316667, 2023). "Authors hypothesized that the profound lymphopenia may have also depleted those factors able to promote the T cell effector function or expansion, and the presence of CD4+ or other immune T cells are also important for promoting and enhancing T cell effector activity against tumor cells." (PMID 37509328, 2023). "Consequently, unlike HPV-unrelated tumors, cases associated with HPV infection are characterized by a high infiltration of immune cells with effector functions directed towards the destruction of the tumor, such as CD4+ and CD8+ T cells, B cells, dendritic cells, and M1 macrophages." (PMID 38136358, 2023). "The observed positive connection between the expression of RECK and the presence of CD8+ or CD4+ T cells implies that the GC patients exhibiting high levels of RECK may also exhibit a higher abundance of T cells in tumor environment, hence potentially indicating a more favorable prognosis." (PMID 37904179, 2023). "Moreover, a recent study revealed that CD4+ T cells might reprogram the TME to a hotter TME by facilitating the normalization of tumor vessels." (PMID 37732493, 2023). "Additionally, treatment with 6-gingerol resulted in a significant influx of tumor-infiltrating lymphocytes such as CD4 and CD8 T-cells, as well as B220+ B-cells, into the tumor microenvironment and this effect can play a role in the anticancer effect of 6-gingerol." (PMID 37687080, 2023). "Concomitant immunity was only partially impacted by CD4 depletion, with significantly larger tumors than mice with primary tumors and no CD4 depletion (p < 0.0001), but significantly smaller tumors than naïve mice (p < 0.01) and approximately half of the mice rejected the second tumor (Fig. 7biii)." (PMID 37072485, 2023). "While co-inhibitory molecule expression was also significantly increased on CD8+ T cell populations compared to at pre-injection, the relative frequencies were lower than CD4+ T cells, which may be due to increased turnover of activated and highly tumour-reactive CD8+ T cells." (PMID 37684239, 2023).
tumor (continued). "Moreover, PD-L1 blockade, CD4+ T cell depletion, or their combination not only increased the proportions of tumor-infiltrating CD44+CD69+CD8+ T cells but also elevated the proportions of central memory CD44+CD62L+CD8+ and effector memory CD44+CD62L−CD8+ T cells, compared with the control group." (PMID 36969495, 2023). "The infiltration abundance of the memory CD4 T cells (P = 0.035), resting NK cells (P = 0.004), M0 macrophages (P < 0.01), M1 macrophages (P = 0.021), and dendritic cells activated (P = 0.011) in tumor samples was significantly higher than that of the normal samples." (PMID 37344840, 2023). "The complexity of CD4+ T lymphocytes (presumably Th2 or Tregs or both) in conjunction with CD8+ T lymphocytes and CD68+ tumor-associated macrophages (TAMs) were also reported that could be predictive of overall survival (OS) and relapse-free survival (RFS) in node-positive human BC." (PMID 37835465, 2023). "However, antigen presentation via HLA-II to CD4+ T cells plays an essential role in the activation of both B-cell and T-cell immune responses, and several studies have demonstrated that neoantigen-specific CD4+ T-cell–directed therapies can inhibit tumor growth." (PMID 37142057, 2023). "Based on the TIMER algorithm, we found that MMP12 expression was significantly negatively correlated with tumor purity (ρ < 0, p < 0.001) and that upregulation of MMP12 expression was associated with increased infiltration levels of five immune cell types (except CD4+ T cells) (ρ > 0, p < 0.05)." (PMID 37601247, 2023). "In addition, CD4+ TILs may recognize antigen in the tumor microenvironment on myeloid cells such as macrophages." (PMID 36512410, 2023). "However, there is also a role for CD4+ T-cells in the interaction between the tumor and TIME." (PMID 37727793, 2023). "Moreover, integrin αvβ3/α6β1 was negatively correlated with memory B cells, activated CD4+ memory T cells and activated mast cells, which could reduce immune cellular functions in the tumor microenvironment (TME) of PCa patients." (PMID 37862114, 2023). "These differentiated CD4+ T subsets, characterized by specific transcription factors, exert a broad range of immune responses in TME; TH1 (T-bet), TFH (BCL6), and TH9 cells are associated with antitumor activity, while TH2 (GATA3), TH17 (RORt), Tregg (FOXP3) cells promote tumor growth." (PMID 36672677, 2023). "Thus, it is tempting to speculate that combining SLAMF7 agonists with personalized vaccines could be a promising strategy to specifically amplify cytotoxic anti-tumor CD4+ T cell responses." (PMID 37965314, 2023). "Moreover, it has been reported that αVβ6 integrins on CD4+CD25+ T cells also inhibited the cytotoxic effects of CD8+ T cells by activating TGF-β, which reduced pro-inflammatory tumor-associated macrophage aggregation towards tumors, thereby suppressing anti-tumor immunity." (PMID 37047140, 2023). "Notably, CD8+ T cells were the only immune cell population with consistent tumor infiltration, while other immune cells, such as CD4+ memory T cells, granulocytes, or M1 macrophages, were found within the tumor boundaries in only 15.5%, 8.4%, and 23.9% of the samples respectively." (PMID 38125025, 2023). "Indeed, specific CD4+ T-cell responses are also closely related to the tumor-killing effect." (PMID 36776837, 2023). "We discovered that CD4+ T cells, CD8+ T cells, Tregs, and macrophages were highly enriched in both groups using risk group-based immunological annotation analysis, which may indicate a potential fundamental regulation between tumor immunity and BM." (PMID 37089260, 2023). "In addition, the tumor-invasive capacity of CTLs can be promoted by CD4+ T cell." (PMID 38082437, 2023). "On the other hand, the anti-inflammatory properties of IL-1Ra may suppress anti-tumor immunogenic responses, as it can inhibit production of effector cytokines in CD4 T cells and antigen-specific T cell responses in mice that have been immunized with tumor neoantigens." (PMID 37563620, 2023).
tumor (continued). "Consequently, in peripheral tissues and blood, the majority of T cells have maintained expression of just one of such co-receptors with distinct roles, with CD8 T cells directly engaged in cytotoxicity against tumor or infected cells and CD4 T cells orchestrating the immune response." (PMID 36960295, 2023). "Notably, the number of NK cells was negatively associated with PFS and OS, which is contrary to the association of memory CD4+T and CD8+T. NK cells participate in tumor immunosurveillance by monitoring and killing tumor cells in an antigen-independent and antigen-dependent manner." (PMID 37346066, 2023). "Furthermore, CD4+ T cells can induce direct cytotoxicity in MHC II expressing tumor cells." (PMID 36776340, 2023). "Disturbances in the DC maturation process and the abolition of their function as APC cells, which prevents the proper presentation of tumour antigens to naïve immune cells in tumour-draining lymph nodes, and the subsequent priming of immunocompetent cells and activation of CD4+ T cells, may occur." (PMID 36980527, 2023). "Furthermore, migration of IL-10-secreting regulatory CD4+ T cells (Tregs) into the tumor environment can be induced by EBNA1-mediated upregulation of CCL20 on tumor cells, leading to the induction of immune tolerance through the suppression of cytotoxic CD8+ T cells." (PMID 37033971, 2023). "Tumor peptide vaccines mainly based on HLA-restricted antigen epitope which could induce both CD4+ and CD8+ immune response against specific tumor-associated antigens (TAA) or tumor-specific antigens (TSA) which highly expressed in cancer cells and not in normal tissues." (PMID 37691932, 2023). "Therefore, association of VISTA expression levels and T cells markers for CD8+T cells, CD4 +T cells and regulatory T cells were assessed in order to evaluate their prognostic significance as well as their potential role in regulating anti-tumor immunity in UM microenvironment." (PMID 37662962, 2023). "Furthermore, HNSCC-56 CIITA tumor cells also grew uninhibited in the presence of CD4+ TILs." (PMID 36512410, 2023). "In veterinary and human searches, a high count and ratio of circulating leukocytes (CD4+ and CD8+ T cells, dendritic cells, macrophages and regulatory T cells), as well as their presence in the tumour microenvironment, may be associated with the prognosis of certain solid tumours." (PMID 37958147, 2023). "Our results suggest that the expression of IL17RB may influence the anti-tumor functions of CD4 Tem, memory B, and activated NK cells, and IL17REL may influence the anti-tumor functions of CD8Tcm, memory B cells, M1 macrophages, and Helper T cells in HPV-positive HNSCC tumors." (PMID 37111458, 2023). "Tregs are a subset of CD4+ T cells that are induced by transcription factors such as FOXP3 and are responsible for autoimmune tolerance and homeostasis, suppressing the excessive immune response that causes allergic and autoimmune diseases, and promoting tumor progression." (PMID 36769116, 2023). "However, LYG1 may play a role in antitumor function by promoting the activation, proliferation, and function of CD4 + T cells in tumor microenvironment." (PMID 37658903, 2023). "In vitro generated moDC essentially behaved like our ex vivo isolated moDC in that they did not specifically respond to activated CD4+ T-cells as compared to naïve CD4+ T-cells and did not relay help for tumor-cell associated antigen cross-priming as compared to the helped cDC1." (PMID 36639382, 2023). "Furthermore, tumor infiltration by plasma cells can participate in the recruitment of CD8+ and CD4+ T-cell and follicular dendritic cells in organized lymphoid aggregates inside tumor stroma, resembling lymph nodes architecture and called tertiary lymphoid structures (TLS)." (PMID 38164130, 2023). "However, CD4+ cells play a complex role in tumorigenesis and tumor progression." (PMID 36835933, 2023).
tumor (continued). "However, some additional CD4+ T cells are immunosuppressive cells, which are involved in immune escape of tumor cells; thus, when the infiltration levels of these cells increased in the TME, in turn promoting tumor progression and contributing to poor prognosis." (PMID 37965307, 2023). "Furthermore, the TCRs identified in this study were isolated from polyclonal CD4+ T cells following tumor rejection, likely reflecting a memory population; TCRs collected from the effector phase during tumor growth may have more diverse functional properties." (PMID 37400675, 2023). "Further studies could evaluate the contribution of CD4+ versus CD8+ tumor-infiltrating T cells to the observed response to elraglusib and anti-PD-L1 therapy, especially considering the recent interest in the contribution of CD4+ helper T cells to anti-tumor immunity." (PMID 37446056, 2023). "Additionally, the administration of CD4+ cytotoxic T cells can lead to an anti-tumor response." (PMID 38328405, 2023). "The results showed that B, naïve plasma, T, CD4 memory resting, resting NK, and other immune-related cells were significantly downregulated, revealing the biological mechanism in which genes may be involved in tumor immune microenvironment." (PMID 37397256, 2023). "Noteworthily, the tumor cured mice treated with NCPA were shown a significant increment of the whole CD4+ and CD8+ T cells as well as central memory CD4+ and CD8+ T cells in both spleen and TDLN, demonstrating the NCPA could potentially elicit immune memory to prevent tumor recurrence." (PMID 37132609, 2023). "Indeed, in murine tumor models, treatment combined with ICI and IL-6 blockade was reported to lead to increased tumor shrinkage in vivo, with a higher density of CD4+/CD8+ effector T cells and reduction of Th17, macrophages, and myeloid cells within tumor tissues." (PMID 38469154, 2023). "Second, the tumor microenvironment generated by injection of CIITA-tumor cells was dramatically different from the one generated by parental cells in that a much stronger infiltration of lymphocytes was observed, with rapid infiltration of CD4+ Th cells preceding infiltration of DC and CD8+ T cells." (PMID 37467968, 2023). "However, OrfV intervention did augment tumor-directed CD4+ T cell responses within the ascites TME." (PMID 38075247, 2023). "On the contrary, unleashing effector CD4+ T cells could robustly enhance anti-tumor responses." (PMID 38062068, 2023). "In addition, SLC1A5 expression was positively correlated with the number of tumor-infiltrating B cells, CD4+ T cells, CD8+ T cells, macrophages, neutrophils, and dendritic cells in HCC and low-grade glioma (LGG), indicating its role in regulating tumor immunity." (PMID 36902385, 2023). "In contrast, DPEP1, HADH, PLIN2, SCD5, SLC44A4, and UGT8 may function to suppress tumor growth via the regulation of immune cells with antitumor activity such as resting memory CD4 T cells, resting NK cells, M2 macrophages, resting and activated DCs, and resting mast cells." (PMID 38090559, 2023). "Moreover, TGF-β skews CD4+ T cells to Tregs and shifts macrophages and neutrophils to anti-inflammatory phenotypes, which promote tumor growth and metastasis via various mechanisms, such as angiogenesis, lymphangiogenesis, and epithelial-mesenchymal transition (EMT)." (PMID 37929901, 2023). "The unfavorable outcome in this group of NMIBC patients might be associated with TIL dysfunction caused by the lack of CD4+ cells in the tumor microenvironment, which play a key role in antitumor immunity." (PMID 38067231, 2023). "Furthermore, the CIBERSORT results indicated a positive correlation between NCAPD2 expression and the 5 subtypes of Tumor-infiltrating immune cells (TIICs), including T cells CD4 memory activated, NK cells resting, Macrophages M0, Macrophages M1, and Mast cells activated." (PMID 36701707, 2023).